MIR1287 (microRNA 1287)
Synonyms: hsa-mir-1287; MIRN1287; mir-1287
Gene: MicroRNA gene on chromosome 10 (98,395,218 to 98,395,307, reverse strand). Ensembl gene ENSG00000284415.
Gene Ontology:
Biological process: miRNA-mediated post-transcriptional gene silencing
Cellular component: RISC complex
Homologues: Orthologues: chimpanzee MIR1287 (100% identical).